CD4 (CD4 molecule)
Diseases named in the same sentence as CD4 in open-access papers (continued):
Sharing a sentence is not in itself a finding about the gene and the disease.
tumor (continued). "Peptide-based tumor vaccines are currently subject to certain limitations in clinical trials, including the challenge of inducing a sustained response from CD4+ T helper cells and cytotoxic T lymphocytes (CTL), as well as human leukocyte antigen (HLA) restrictions." (PMID 38961429, 2024). "Interestingly, depletion of CD8 T cells largely abrogated the inhibition of tumor growth in this study, with a minor contribution from CD4 T cells." (PMID 39125578, 2024). "Several other factors, such as moderate affinity, critical epitope targeting and a higher CD4/CD8 ratio may also contribute to the anti-tumor activity, although further investigation is needed." (PMID 38637886, 2024). "Importantly, one of the key features of human MDSCs in cancer patients is the downregulation of major MHC-II, making them less prone to present tumour epitopes thus refraining from stimulating CD4+ T cells." (PMID 38464388, 2024). "Similarly, treatment of B16 melanoma-bearing mice with T. gondii excretory–secretory antigens suppressed tumor growth and led to a decrease in CD4+ CD25+ Treg cells and an increase in NK cells." (PMID 39367471, 2024). "We further show that a similar CD4+ T cell population can be found in progressively growing tumours in mice as they become insensitive to anti-PD1 therapy and in human patients with cancer who respond poorly to immune checkpoint therapy (ICT) and cancer vaccines." (PMID 39048822, 2024). "We confirmed that the majority of tumor-infiltrating lymphocytes were CD4+ T cells." (PMID 38562932, 2024). "This highlights the importance of CD4+ T cells in tumor immunity." (PMID 39106430, 2024). "Several pre-clinical cancer vaccine studies confirmed that CD4+ T cell help is required to induce effective and durable anti-tumor responses, even to MHC class II-negative tumors, and that the presence of tumor-specific help enhances neoantigen-specific CD8+ T cell responses." (PMID 39040850, 2024). "Moreover, in an experimental model of mammary tumor vaccination, ATRA activity reverts tumor-induced CD4+ T-cell tolerance." (PMID 38360674, 2024). "In addition, surface expression of T cell activation markers CD69 and CD25 elevated in both CD8+ and CD4+ T cells in the presence of CFPAC-1 tumor cells and HLA-G12V/CD3 BiTE." (PMID 38752985, 2024). "Studies have shown that multiple tumor-derived extracellular vesicles can act on CD4+ T cells." (PMID 38816455, 2024). "This may suggest that Neo-CT promotes an increased migration of CD4+ T cells toward tumor-rich areas, whereas CD8+ T cells accumulates in peritumoral areas." (PMID 38335302, 2024). "Therefore, MLTC was used to examine the proliferation of splenic CD4+ T cells derived from tumor-bearing Rab37 WT and KO mice by CFSE assay." (PMID 38321486, 2024). "Furthermore, antibodymediated depletion of either CD4+ or CD8+ T cells abrogated NP-GSDMA3 treatment-induced tumor regression, indicating that tumor regression due to pyroptosis required both CD4+ T helper cells as well as cytotoxic CD8+ T cells." (PMID 38391959, 2024). "Additionally, we utilized IHC to evaluate the CD4 expression within FL tumor tissues as IHC is the most widely employed technique in both clinical and pathologic practices, and it has the characteristics of convenience, simplicity, and repeatability." (PMID 39248131, 2024). "We also evaluated changes in the TiME by analyzing tumor‐infiltrating CD3+CD4+ and CD8+ T cells." (PMID 38063844, 2024). "In the tumor microenvironment, CD4 + T cells may play a critical role in reducing immune tolerance to tumor antigens, thereby enhancing immune responses." (PMID 38609993, 2024). "Additionally, CD4+ T cells contribute to the anti-tumor arsenal by secreting key effector cytokines, such as IFNγ and TNFα." (PMID 38892411, 2024).
tumor (continued). "However, in HPV-negative HNSCC patients, LAYN was positively correlated with infiltrating B cells (P < 0.01), CD4 + T cells (P < 0.001), macrophages (P < 0.001), neutrophils (P < 0.05), and dendritic cells (P < 0.001) in tumor tissues." (PMID 38430385, 2024). "Tumor immune infiltration analysis showed that ROMO1 expression in COAD, LIHC, PAAD, and STAD was associated with the infiltration of immune cells (B cells, CD4+ T cells, CD8+ T cells, neutrophils, macrophages, and dendritic cells)." (PMID 39727991, 2024). "Since we observed a significant increase in the lymphoid fraction pre‐ versus posttreatment in the PI3K/mTORi‐ and PI3K/mTORi+PD‐1i‐treated tumours, we further analysed the TILs and, based on marker gene expression, identified NK‐cell, CD4+ and CD8+ T‐cell populations." (PMID 38711203, 2024). "However despite this, it is striking how poor B cells were at activating the tumour-specific CD4 T cells in one of the most lymphopenic systems available to study in mice." (PMID 38125720, 2024). "Notably, analysis of TLSs revealed that not only CD20+ B cells were present in the TLSs of the tumor, but they also colocalized with CD4+, CD8+, and FOXP3+ T cells." (PMID 39473903, 2024). "Additionally, combined treatment remarkably upregulated tumor-infiltrating CD4+ immune cells compared to local radiotherapy alone (p < 0.05)." (PMID 38821980, 2024). "Thus, we aimed to explore the spatial relationship between CD8+ T cells, CD4+ T cells, and tumor cells." (PMID 38611111, 2024). "While this can lead to the sequestration of CD8+ T cells away from the tumor, as the authors pointed out, increasing the trafficking of CD4+ cells, especially naïve ones, can lead to the increased accumulation of Tregs due to the immunosuppressive molecular signals present in the PDAC TME." (PMID 38339310, 2024). "OCSC-derived exosomes polarize tumor-associated macrophages (TAMs) into M2 macrophages by transferring UCA1, which targets the LAMC2-PI3K/AKT signaling pathway, further suppressing anti-tumor immunity including CD4+ T cell activation and interferon-γ production." (PMID 39200273, 2024). "Harnessing HLA-II–restricted TCRs from CD4+ T cells may promote systemic antitumor immunity and overcome defects in HLA-I expression in tumors, and on its own, CD4+ TCR-T has mediated tumor regression in humans." (PMID 39484723, 2024). "Also, TIME composition varied by tumor site with AdCC of the minor glands having more CD4+ T cells than major glands, the submandibular glands being more enriched for plasma cells, and the parotid gland being more enriched for NK cells." (PMID 38982149, 2024). "Additionally, CD4+ T cells possess the ability to directly eliminate tumor cells by releasing cytotoxic particles." (PMID 39845973, 2024). "However, CD4+ T cells of the Th2 subtype release anti-inflammatory molecules that have tumor-promoting properties." (PMID 38933335, 2024). "Similarly, we examined the effector functions of tumor-infiltrating CD4+ T cells in CD8+ T cell-depleted mice." (PMID 39185202, 2024). "CD8+ T cells, CD4+ T cells, and NK cells can eliminate tumor cells, exerting anti-tumor effects." (PMID 38928496, 2024). "However, it has also been noted that the high level of CD4+ T cell distribution within a distance of 0-10 μm from the tumor cells predicts a low survival rate." (PMID 39703499, 2024).
tumor (continued). "In addition, CTLA4 pathway can also significantly enhance the secretion of IL-2 by CD4+T cells and promote the proliferation, survival and tumor killer activity of T, NK and other immune cells in the tumor microenvironment." (PMID 38713378, 2024). "Cytotoxic CD8 + T lymphocytes and CD4 + helper T cells can attack antigenic tumor cells and prevent the spread of cancer, while antigenic tumor cells can be targeted by these cells to prevent tumor growth." (PMID 39465721, 2024). "A recent clinical trial revealed that the standard GBM therapy incorporated with the administration of HSPPC-96, as a TLR4 agonist derived from a patient's tumour, potentiated infiltration of CD8+ and CD4+ T cells in the injected tumours and upregulated the immune-related genes." (PMID 38698968, 2024). "CD4+ T cells may kill HLA II–negative tumors when tumor antigen is processed and presented by antigen-presenting cells (APCs)." (PMID 38412034, 2024). "Additionally, HSYA regulated the polarization of CD4+T cells within the tumor immune microenvironment, ultimately blocking cancer cell proliferation, transformation, and metastasis, leading to apoptosis." (PMID 39877386, 2024). "Additionally, populations of Tregs (CD4+CD45RA−FOXP3+) decreased while CD8+ T cells increased among tumor-infiltrating lymphocytes." (PMID 38339310, 2024). "Notably, anti-HER2/neu IgG3-(GM-CSF) is a full IgG ICK fused to GM-CSF that accumulated in the tumor and spleen in animal models and was able to enhance both CD4+ Th1- and Th2-mediated immune responses and reduce tumor growth in anti-HER2-resistant tumors." (PMID 39204319, 2024). "Furthermore, pre-clinical evidence on GITR-agonist monotherapy has demonstrated antitumor effect via enhancing CD8+ and CD4+ effector T-cell activity and depleting tumor-infiltrating Tregs, which are considered the main GITR expressors." (PMID 39061246, 2024). "In the current study, by performing multivariate analysis including baseline characteristics and ELN-defined genetic risk category, we found that a lower proportion of CD4 Tem at diagnosis independently predicted poorer RFS in AML, which coincided with superior anti-tumor capacity of memory cells." (PMID 39100667, 2024). "Furthermore, conditions in the TME are also able to differentiate CD4+ T cells into Treg cells, destroying the host immune system and enhancing the immunosuppressive effects of MDSCs to activate tumor dormancy and evade immune system surveillance." (PMID 38404689, 2024). "High levels of circulating MDSCs correlate with liver and bone metastases and higher levels of circulating tumor cells, while the presence of tumor-infiltrating lymphocytes (TILs) like CD4+ and CD8+ T cells in tumors is positively correlated with BrCa prognosis." (PMID 39195207, 2024). "The high correlation of CD8 T cells with monocytes, activated mast cells, naive CD4 T cells, M0 macrophages, resting CD4 T memory cells, activated CD4 memory cells, follicular helper T cells, Tregs and M1 macrophages suggests their interplay in the tumor microenvironment." (PMID 39006030, 2024). "Similarly, COL4A6 was positively correlated with macrophage, neutrophil and CD4 + T cell immune infiltration, however, negatively correlated with tumor purity." (PMID 38907304, 2024). "TCR135-engineered primary CD4+ T cells specifically recognized HLA-DP5+EBNA1+ tumor cells." (PMID 38412034, 2024). "The CD4+ T, NK, and plasma cell populations also vary by tumor subsites, suggesting that the observed submandibular AdCC tumor-intrinsic pathway differences may be responsible for influencing the TIME composition and survival differences." (PMID 38982149, 2024).
tumor (continued). "Conversely, Th2 subtype CD4+ T cells secrete anti-inflammatory mediators, promoting tumor growth." (PMID 39926600, 2024). "In tumor immune infiltration analysis, we could find that immune cells (CD4+ T cell and M1 macrophage) with higher levels of infiltration in the low-risk group which play a role in consistent tumor growth in the tumor microenvironment." (PMID 38379084, 2024). "It’s worth noting that CD4+ T cells identify distinct surface markers compared to CD8+ T cells, and given that cancer cells generally lack MHC-II expression, CD4+ T cells demonstrate effectiveness in exerting tumor suppression through interactions with stromal cell surface markers." (PMID 39058687, 2024). "Moreover, a reduction in tumor-infiltrating CD4 and CD8 T cell populations was also observed in myeloid-specific FIH deficient mice." (PMID 38422022, 2024). "Furthermore, CD40L-actived B cells of HCC patients were able to induce in vitro CD4+ and CD8+ responses in autologous TIL fractions to tumour-associated antigens (glypican-3, MAGE-C2)." (PMID 38440738, 2024). "Moreover, immunofluorescence of tumor-draining lymph node sections confirmed that the population expressing the highest level of PD-1 were indeed CD4+ T cells located in germinal centers." (PMID 38417020, 2024). "Nevertheless, the differential gene expression analysis showed that TGF-β-TRAP suppresses the granulocyte degranulation and CD4+ T cell response to granulocyte degranulation signals, consistent with a published study showing TGF-β reprograms tumor-associated neutrophils." (PMID 39298276, 2024). "Considering the levels of TILs pre‐ versus posttreatment (normalised against tumour cell population), we observed a significant increase in both the CD4+ and CD8+ T‐cell/tumour cell ratios, in the PI3K/mTORi‐ and PI3K/mTORi+PD‐1i‐treated conditions but not in the PD‐1i‐ or vehicle‐treated tumours." (PMID 38711203, 2024). "Conversely, CD4+ T cells can have dual roles; while they can enhance antitumor immunity, certain subsets may promote tumor progression, particularly in the context of chronic inflammation." (PMID 39690926, 2024). "Cellchat analysis revealed that TCR+ Macrophages displayed the closest interaction with CD4+ T cells in tumor tissues from responsive patients, whereas TREM2+ Macrophages were predominantly associated with CD4+ T cells in tumor tissues from non-responsive patients." (PMID 38948071, 2024). "In addition to cascading with pro‐inflammatory signaling pathways, PIK3CD overexpression is also closely associated with the activation of tumor‐infiltrating immune cells such as CD8+ and CD4+ T lymphocytes, which is analyzed by TIMER algorithm." (PMID 38545256, 2024). "In addition, activated CD4+ T cells can not only play an auxiliary role in enhancing the clonal expansion and antitumor activity of CTLs but kill tumor cells through direct cytotoxic effects." (PMID 38348027, 2024). "Inducing CD4+ Th1-dominant immunity is the main target for tumor immunotherapy." (PMID 38827732, 2024). "In coordination with CD4+ T cells, this suppresses tumor progression." (PMID 39811730, 2024). "Besides, an increase in B cells was observed in the combined treatment No remarkable differences were observed in the proportions of tumor-infiltrating CD4+ T cells and natural killer (NK) cells." (PMID 38643157, 2024). "IL-2, while supporting CD8+ expansion, also acts upon CD4+ Tregs, which may in turn limit the net anti-tumor benefit of administering IL-2 alone." (PMID 38928238, 2024). "In addition, CD4+ T-cell memory cells were predicted to be more abundant in tumor-sparse regions while CD8+ T-cell memory cells were more abundant in tumor-rich regions." (PMID 39001353, 2024). "However, tumor-bearing CD11c:DTA mice displayed the profound reduction of Ag-specific divisions of OT-I CD8+ T cells in tumor tissues and TdLNs as well as OT-II CD4+ T cells in TdLNs as compared with tumor-bearing WT mice." (PMID 39206204, 2024).
tumor (continued). "Interestingly, the average minimum distance from B cells, CD8+T cells, CD4+T helper cells, and Tregs to tumor cells was shortest in tumors originating from the oral cavity." (PMID 39053947, 2024). "Therefore, in-depth understanding and research on the functions and regulatory mechanisms of CD4+ T cells will help to develop new CAR-CD4+ T anti-tumor therapies." (PMID 39372416, 2024). "Moreover, we observed heightened expression of IFN-γ and TNF-α effector cytokines in CD4+ T cells within the tumor-draining lymph nodes (dLN) of Flot2CD4 mice." (PMID 39499901, 2024). "In a model of spontaneous melanoma, IL4I1 expression and activity increases with disease progression, while IL4I1 deficiency enhances tumor control and associates with reduced G-MDSC and macrophage infiltration as well as enhanced CD4+ T-cell, CD8+ T-cell and B-cell infiltration into the tumor." (PMID 39211039, 2024). "In addition to the low expression of PD-L1 in tumor cells, various factors such as low expression or deletion of MHC I and MHC II proteins in the tumor microenvironment, and inhibition of the proliferation of CD4+ cells can also contribute to immune escape." (PMID 39144829, 2024). "Enhancing the activity of CD62L on monocyte and resting Treg%CD4 cells in tumor immunotherapy is expected to improve the therapeutic effect and may become an important part of future tumor immunotherapy strategies." (PMID 38953025, 2024). "Importantly, the ratio of CD4+ to CD8+ T cells correlates with tumor lymphatic metastasis and overall survival." (PMID 39329710, 2024). "Additionally, a study showed that CD4+ T cells that are deficient in the ER stress chaperone GRP94 cannot be activated due to defective Ca2+ mobilization, leading to inhibition of tumour progression." (PMID 38297380, 2024). "This CD4+ TRM cell-initiated anti-tumor immunity was dependent on NK cells and IFN-γ, and the CD4+ TRM/NK cell axis could orchestrate the formation of TME, inhibiting the expansion of MDSCs." (PMID 38892411, 2024). "In addition to CD8+ T cell responses to HLA-I neoantigens, which mediate tumor rejection by direct killing, induction of CD4+ T cell responses to HLA-II neoantigens have been repeatedly reported in preceding neoantigen vaccine clinical trials." (PMID 39292790, 2024). "Given the predominant localization of Tcm_CD4 within secondary lymphoid organs, a decrease in Tcm_CD4 cell attributed to low WFS1 expression may contribute to an increased likelihood of tumor tissue metastasis to the lymph nodes." (PMID 39478865, 2024). "Additionally, they noted increased tumor infiltration by TH1 CD4+ T cells and cytotoxic CD8+ T cells after antibiotic-mediated microbiota depletion in NODSCID mice harboring human PDAC xenografts." (PMID 39044834, 2024). "Tumor-specific B cells interact with CD4+ T cells and Tfh cells to enhance CD8+ T cell action." (PMID 39840050, 2024). "Additionally, the spleen exhibited a similar ratio of CD4+ to CD8+ T cells, where the presence of CD4+ cells enhanced long-term tumor cell-killing capacity and sustained proliferation." (PMID 38953027, 2024). "We hypothesize that the time point post-treatment plays a role in the infiltration of CD4+ T cells into the tumor." (PMID 38523774, 2024). "Higher infiltration levels of CD8 and CD4 T cells indicate better prognosis in tumor patients." (PMID 39513664, 2024). "Using a composite of intracellular and cell surface proteins, four major subsets of CD4+ T cells, from which Treg cells are derived, are classified as non-Treg, naïve Treg, effector Treg and tumor-associated effector Treg cells." (PMID 38318526, 2024). "To identify the major populations and subpopulation compositions of tumor infiltrating immune cells, we performed clustering using Seurat to identify the major immune cell types, including NK cells, CD4+ T cells, CD8+ T cells, cycling T cells, myeloid cells, and B cells." (PMID 38622125, 2024).